CAT (catalase)
Diseases named in the same sentence as CAT in open-access papers (continued):
Sharing a sentence is not in itself a finding about the gene and the disease.
glioma (continued). "Overall, this study provides strong evidence suggesting that overexpression of CAT in glioma cells leads to increased resistance to TMZ and radiation, suggesting an essential role of H2O2 in the molecular mechanism by which these treatments lead to tumor cytotoxicity." (PMID 34943091, 2021). "Furthermore, this lactone decreased glioma cell migration and modulated redox status, increasing superoxide dismutase and catalase activities and enhancing sulfhydryl content, consequently suppressing reactive species of oxygen generation." (PMID 30420941, 2018). "In this context, we measured the activity of two antioxidant enzyme types, SOD and catalase, involved in maintaining cellular redox balance, in the cellular lysates of glioma C6 cells treated with 5, 10, 15 and 20 μg/ml Cas III-ia for 24 h as well as in controls." (PMID 22540380, 2012). "Finally, CAT overexpression in advanced or treatment-exposed gliomas may represent an adaptive resistance mechanism, enabling tumor cells to mitigate therapy-induced oxidative stress and enhance survival." (PMID 41009025, 2025). "Importantly, pharmacological inhibition of CAT activity led to reduced proliferation of glioma cells derived from patient biopsies, suggesting that targeting CAT could be a potential therapeutic strategy to overcome resistance in glioblastoma." (PMID 41009025, 2025). "In particular, controversy remains as to whether CAT is up- or downregulated in gliomas." (PMID 34943091, 2021). "Interestingly, CAT-overexpressing cells were also resistant to treatment with staurosporine (10 μM), a well-known inducer of apoptosis, suggesting that CAT-overexpressing glioma cells are resistant not only to TMZ but to apoptotic stimuli in general." (PMID 34943091, 2021). "The presented results confirm disturbances in redox homeostasis in U-87 glioma cells under the influence of NaF, manifested by increased ROS production and modulation of SOD and CAT activity." (PMID 40497976, 2025). "The higher variability in CAT and NFE2L2 expression was observed in glioma biopsies, which also had the highest expression levels." (PMID 33540681, 2021). "Our previous studies also revealed increased expression of CAT, superoxide dismutase 2 (SOD2), and BMI1, a protein related to stemness and therapy resistance, in TMZ-resistant glioma cells." (PMID 34943091, 2021). "Moreover, U251 cells overexpressing CAT formed neurospheres in neurobasal medium, whereas control cells did not, suggesting that the radio- and chemoresistance conferred by CAT may be due in part to the enrichment of glioma stem cell populations." (PMID 34943091, 2021). "In support of this, previous studies have shown that antioxidant proteins catalase and PRDX2 are also highly expressed in glioma cells." (PMID 22916164, 2012). "Inhibition of catalase activity and decreasing PRDX2 expression sensitized glioma cells to oxidative stress and ionizing radiation, respectively." (PMID 22916164, 2012). "Exposure of glioma cells to sodium fluoride leads to moderate disturbances in the antioxidant system (transient decrease in SOD activity at low dose and tendency to decrease in CAT); however, the overall glutathione level remains relatively stable." (PMID 40497976, 2025). "Silencing CAT in murine glioma cells was found to increase intracellular ROS and extracellular H2O2, resulting in improved radiosensitivity; however, pharmacological inhibition of CAT cannot produce an effect on cell viability unless additional OS is induced via oxidants or radiation." (PMID 36307808, 2022). "In fact, both C6 GB cells and normal astrocytes were treated with PPAR-α and PPAR-γ agonists, showing a significant increase in catalase expression only in normal astrocytes, while, on the contrary, they failed to increase catalase expression in glioma cells." (PMID 35203272, 2022).
glioma (continued). "Compared with the expression in non-tumor tissue, CAT mRNA expression was significantly upregulated in astrocytoma, oligodendroglioma, mixed glioma, and GBM samples." (PMID 34943091, 2021). "Furthermore, eDCM and eEtAc also reduce oxidative damages against glioma cells due to increase of SOD, CAT and GPx antioxidant enzymes consequently, decrease of ROS production." (PMID 30420941, 2018). "We next investigated the enzymatic activities of catalase, MnSOD and GPx1 in GSCs and non-GSCs glioma cells." (PMID 26124081, 2015). "Reductions observed in the nucleus and mitochondria do not necessarily indicate a decrease in total cellular CAT, as glioma cells may redistribute CAT to the cytoplasm or regulate its expression differently across compartments." (PMID 41009025, 2025). "Moreover, glioma cells that stably overexpress SOD and CAT exhibit high resistance to TMZ, enhanced tumorsphere formation, and poor prognosis, and TMZ-resistant glioma cells display increased expression of CAT, SOD2, and BMI1, a protein associated with stemness and therapy resistance." (PMID 40298811, 2025). "Catalase and MnSOD were constitutively expressed in all tested GSCs and non-GSCs glioma cells." (PMID 26124081, 2015). "In in vitro rat cell models, activation of PPARγ transcription has been shown to upregulate catalase activity in normal astrocytes, but not in the glioma C6 cell line.Moreover, this effect was abolished in cells transfected with a dominant negative PPARγ construct." (PMID 24672773, 2014). "Subsequent studies demonstrated that the electrotaxis of glioma cells were abolished by the superoxide inhibitor N-acetyl-l-cysteine (NAC) or overexpression of mitochondrial superoxide dismutase (MnSOD), but was not affected by inhibition of hydrogen peroxide through the overexpression of catalase." (PMID 23613809, 2013). "In glioma C6 cells, exposure to Cu (II) complexes increased SOD and CAT activity, but not GPx activity." (PMID 35741335, 2022). "The directional cathode migration of glioma cells was abolished by the application of NAC or overexpression of SOD, but was not affected by the overexpression of CAT." (PMID 23613809, 2013). "Because the overexpression of CAT can inhibit the activation of JNK and p38, but cannot inhibit the directional migration of glioma cells, JNK and p38 may not play a role in this response." (PMID 23613809, 2013).
cardiac hypertrophy (31 papers, 2011 to 2025). "In fact, the activation of catalase by apelin can prevent oxidative stress-linked cardiac hypertrophy." (PMID 34439471, 2021). "Thus, the present work aimed to examine the effect of PPARδ activation on catalase expression to determine whether there is a mechanistic link between vasoactive peptide Ang II-associated cardiac hypertrophy and PPARδ-mediated upregulation of catalase." (PMID 34439471, 2021). "It has been previously demonstrated that FoxO3 activates the expression of catalase in response to oxidative stress, thereby inhibiting cardiac hypertrophy." (PMID 40785055, 2025). "SIRT3 has been previously demonstrated to counteract cardiac hypertrophy in primary cultures of cardiomyocytes by activating MnSOD and catalase, thereby decreasing cellular levels of ROS." (PMID 37558995, 2023). "Inhibition of mitochondrial ROS production by SS-31 or genetic transfer of catalase targeted to mitochondria was found to prevent Ang II-induced cardiac hypertrophy, and diastolic dysfunction in mice." (PMID 36359731, 2022). "It is also increasingly evident that increased ROS and oxidative stress also result from the activities of endogenous antioxidants such as superoxide dismutase, glutathione peroxidase, and catalase in Ang II-induced cardiac hypertrophy." (PMID 36359731, 2022). "Carvacrol administration with different doses (25, 50 and 75 mg/kg) exerts a cardio‐protective role against cardiac‐hypertrophy of male Wistar rats via increasing catalase and mRNA expression." (PMID 36348778, 2022). "SIRT3 interacts with FOXO3a to activate antioxidant genes, such as MnSOD and catalase, the products of which can reduce the level of ROS and positively affect disorders such as interstitial fibrosis and cardiac hypertrophy." (PMID 35571098, 2022). "It was found that SIRT3 activates SOD2 and catalase to block cardiac hypertrophy in primary cardiomyocytes cultures, thereby decreasing ROS levels." (PMID 35571098, 2022). "We identified catalase as an effector molecule in the PPARδ-mediated reduction of ROS accumulation, thereby preventing cardiac hypertrophy induced by Ang II." (PMID 34439471, 2021). "Catalase is also known to involved in the suppression of oxidative stress-induced cardiac hypertrophy." (PMID 34439471, 2021). "We observed that Catalase was critically involved in the function of JMJD1A because Catalase knockdown blocked the protective function of JMJD1A during cardiac hypertrophy." (PMID 32461996, 2020). "On the contrary, cardiac-specific overexpression of catalase alleviated aging-related cardiac dysfunction and cardiac hypertrophy." (PMID 33014281, 2020). "Here, we showed that JMJ1A participated in cardiac hypertrophy via targeting catalase to regulate oxidative stress." (PMID 32461996, 2020). "These protective effects of mitochondrial catalase expression extended to the TAC model of cardiac hypertrophy and HF." (PMID 31857574, 2019). "Because previous reports suggest that the accumulation of ROS in diabetic mice leads to cardiac hypertrophy 25, 26, we next compared the levels of ROS in myocardial tissues of WT and CAT‐TG diabetic mice." (PMID 28643395, 2017). "Constitutively expressed Sirt3 was shown to reduce ROS in adipocytes, and the increased expression of Sirt3 protected myocytes from genotoxic and oxidative stress and blocked cardiac hypertrophy by activating antioxidant enzymes such as MnSOD and catalase." (PMID 21390294, 2011). "By comparing the effect of overexpression of mitochondrial targeted catalase (mCAT) with overexpression of peroxisome targeted catalase (pCAT) in mice, it can be shown that AngII-induced cardiac hypertrophy, fibrosis and mitochondrial damage is somewhat less in mCAT-overexpessing mice than WT mice." (PMID 36632466, 2023). "Furthermore, forkhead transcription factor Foxo3a-mediated transcriptional regulation of catalase inhibits cardiac hypertrophy by modulating ROS generation induced by insulin." (PMID 34439471, 2021).
cardiac hypertrophy (continued). "SDG has also shown to decrease lipid peroxidation, and to decrease ROS, catalase and superoxide dismutase and glutathione peroxidase activity preventing heart hypertrophy and dysfunction in a rat model of pulmonary arteria hypertension which is known to have robust levels oxidative stress." (PMID 33266301, 2020). "Recently, the protective effect of Sirt3 under oxidative stress was shown in cardiomyocytes, where it was shown that Sirt3 reduced ROS generation in cardiomyocyte under cardiac hypertrophy by enhancing antioxidant enzymes such as manganese superoxide dismutase (MnSOD) and catalase." (PMID 21390294, 2011). "In addition, it has been shown that cardiac hypertrophy in mice improves by reducing cellular ROS levels through upregulation of the antioxidant enzymes catalase (CAT) and superoxide dismutase (SOD), due to SIRT3-mediated deacetylation of FOXO3 (mitochondrial sirtuin)." (PMID 36771251, 2023). "Moreover, some of these genes, including the ones coding for catalase and calpastatin, have been involved in the development of cardiac hypertrophy and could therefore provide the link between Cavβ2 expression and this pathology." (PMID 34307509, 2021). "Sheng Mai San ameliorates heat stress-induced cardiac hypertrophy, enhances the expression of antioxidant enzymes (GSH, SOD, and CAT), activates the Keap1-Nrf2 pathway in the heart, and restores oxidative stress balance." (PMID 40566495, 2025). "A previous study using pressure overload induced cardiac hypertrophy model showed that fisetin markedly reduced ROS by increasing expression of SOD1, CAT and HO1." (PMID 37627641, 2023). "Sirt3 inhibited cardiac hypertrophy by stimulating the Forkhead box O3a-dependent (Foxo3a-dependent), manganese superoxide dismutase (MnSOD) or superoxide dismutase 2 (SOD2) and catalase (Cat), thus suppressing cellular levels of ROS in primary cardiomyocytes." (PMID 35052850, 2022). "The endogenous antioxidant marker glutathione (GSH) and enzymes such as superoxide dismutase (SOD), catalase (CAT), glutathione-S-transferase (GST) were also modulated by heart hypertrophy." (PMID 34226405, 2021). "It was reported that the overexpression of catalase targeted to mitochondria but not wild type catalase in peroxisomes ameliorates cardiac hypertrophy and diastolic dysfunction in mice." (PMID 36093152, 2022). "Mice overexpressing catalase targeted to mitochondria, but not mice overexpressing cytoplasmic catalase, are resistant to cardiac hypertrophy, fibrosis and mitochondrial damage induced by Ang II, as well as to HF induced by overexpression of Gαq." (PMID 25561233, 2014). "Overexpression of catalase targeted to mitochondria, but not the overexpression of wild-type peroxisomal catalase, protects against ANG II-induced cardiac hypertrophy, fibrosis and mitochondrial damage, as well as heart failure induced by overexpression of Gαq." (PMID 27833552, 2016).
Hepatic steatosis (31 papers, 2012 to 2026). Steatosis is a term used to denote lipid accumulation within hepatocytes. "γ-GT, a glutathione catalase protein and the major thiol antioxidant, is associated with the presence of hepatic steatosis and an elevation in serum γ-GT is known as a marker of oxidative stress and correlates with the presence of CVD." (PMID 34552789, 2021). "In this experiment, the HFD, FF, and SD diet treatment had a significant impact on the SOD and CAT activities in both the plasma and hepatic level where the activity is drastically downregulated in hepatic steatosis conditions." (PMID 39803213, 2025). "We further studied the effects of 9-HODE and 13-HODE on liver steatosis and identified CAT as a direct target of 13-HODE." (PMID 38071367, 2023). "Results: the HFHS diet induced, in the dams, hepatic steatosis, oxidative stress (reduced catalase, elevated protein oxidation) and the activation of pro-inflammatory pathways (p38-MAPK), along with imbalanced circulating cytokine concentrations (increased IL-6 and decreased IL-5 and IL-17A)." (PMID 38671859, 2024). "We investigated the effects of CAT on 13-HODE-induced hepatic steatosis in vivo." (PMID 38071367, 2023). "CAT overexpression protects against age-related liver steatosis." (PMID 38071367, 2023). "Furthermore, CAT overexpression improved 13-HODE-induced hepatic steatosis, as evidenced by Oil Red O and Nile Red staining, and decreased liver TG content." (PMID 38071367, 2023). "We also tested the therapeutic effects of CAT overexpression on age-related liver steatosis." (PMID 38071367, 2023). "Therefore, 13-HODE produced by senescent hepatocytes and macrophages activates SREBP1 by directly inhibiting CAT activity and promotes liver steatosis." (PMID 38071367, 2023). "A single dose of human atMSC that had been genetically modified with adenovirus constructs to overexpress one of two antioxidants, either superoxide dismutase 2 (Sod2) or catalase (Cat), improved hepatic steatosis and systemic inflammation significantly after just 4 weeks." (PMID 35860241, 2022). "Interestingly, a recent study reported that i.p. modified human adipose tissue-derived MSCs with antioxidant genes Sod2 (mitochondrial) and catalase (cytosolic) upregulated using adenoviral constructs significantly reduced liver steatosis and TG content." (PMID 32045450, 2020). "Hepatic steatosis was accompanied with an elevation in the hepatic biomarkers of redox status evidenced by a drop in the hepatic catalase and GST levels significantly by about 75% and 57%, respectively, accompanied by an increase in the hepatic MPO level by 3.4 folds." (PMID 32420546, 2020). "BBR treatment likely ameliorated hepatic steatosis and fibrosis by protecting the liver from injury caused by lipoperoxide, because the mRNA expression of CYP2E1 and CYP4A10 was downregulated, and the mRNA expression of catalase was upregulated by BBR." (PMID 26857750, 2016). "Cashew nut oil reduced blood glucose, triglycerides, uric acid, and liver steatosis, and increased SOD expression and activity and catalase activity." (PMID 41103188, 2026). "Cashew nut oil reduced blood glucose, triglycerides, uric acid, and liver steatosis, and increased SOD expression and activity as well as catalase activity." (PMID 41103188, 2026). "Compared with HFHC, both CAB and HECAB reduced serum insulin and HOMA-IR, attenuated hepatic steatosis, increased SOD1 and CAT, and reduced NF-κB, IL-6, TNF-α, and IL-1β, whereas GPx1 remained unchanged." (PMID 42193214, 2026). "Co-exposure to BP3 and HFD significantly worsened hepatic steatosis, as evidenced by increased triglyceride levels, lipid droplets accumulation, and oxidative damage (elevated hepatic MDA levels and decreased hepatic CAT activity)." (PMID 41209729, 2025). "Decreased CAT activity activates SREBP1 further by increasing H2O2 levels and promoting liver steatosis." (PMID 38071367, 2023).